EGFR (epidermal growth factor receptor)
Diseases named in the same sentence as EGFR in open-access papers (continued):
Sharing a sentence is not in itself a finding about the gene and the disease.
adenocarcinoma (continued). "In the IPASS study population (patients from Asia, light, or nonsmokers and diagnosed with adenocarcinoma), 59.7% tumors had EGFR mutation, compared with the mutation rate of 12.1% in the unselected population of the ISEL study." (PMID 28203260, 2017). "The TTF-1-positive adenocarcinomas had a statistically significant prevalence of the female, non-smoker, and associated with the EGFR mutation." (PMID 28783064, 2017). "EGFR rare mutations were significantly associated with female gender (P = 0.000) but not never-smoking and histology of adenocarcinoma (P = 0.061, P = 0.060; respectively)." (PMID 28211502, 2017). "Among HER2-overexpressing adenocarcinomas, 1 (16.7%) and 2 (33.3%) had EGFR and KRAS mutations, respectively, while none had ALK or ROS1 rearrangements." (PMID 28146588, 2017). "Mutations of EGFR, which occur most often in EGFR exons 18–21, are mostly associated with never-smokers, those with adenocarcinoma histology, females, and persons of Asian ethnicity." (PMID 29928550, 2017). "Secondly, lack of relevant studies prevented us from further exploring the prevalence of EGFR mutation in some patient subgroups, such as Asian female non-smokers and Asian female adenocarcinoma patients." (PMID 27738317, 2016). "Previous studies have reported that EGFR mutations had higher frequency in adenocarcinoma than other types of NSCLCs, in never-smoker as opposed to ever-smokers, and in females rather than males." (PMID 27213344, 2016). "In those studies, it was stated that ALK rearrangements were more common in nonsmoking patients, younger patients and adenocarcinoma histology and that it rarely coincided with the presence of an EGFR mutation." (PMID 27217997, 2016). "All patients had stage IV disease at the time crizotinib treatment was initiated, and all tumors were adenocarcinomas with no EGFR/KRAS mutations." (PMID 27418132, 2016). "Because we found a higher frequency of EGFR/KRAS mutations in NSCLC cell lines with high PD-L1 expression (p < 0.001), we evaluated the relationships between downstream signals and PD-L1 expression, particularly in three KRAS-mutant adenocarcinoma cell lines." (PMID 27846317, 2016). "If only adenocarcinoma patients were included in the analysis, female gender, older age, and never-smokers were more likely to have EGFR mutation." (PMID 27191886, 2016). "The clinical characteristics of younger age patients showed unique factors compared to older patients, such as greater proportions of female patients, adenocarcinoma, and never-smoking, and a lower EGFR mutation rate." (PMID 27191886, 2016). "The aim of this study was to compare the statuses of K-ras and EGFR between primary adenocarcinomas of lung and their corresponding brain metastases, and to investigate whether the existence of genetic alterations would influence the outcomes of patients." (PMID 27070580, 2016). "As expected in EGFR mutated patients, adenocarcinoma histology and non-smokers were both frequent characteristics." (PMID 27926478, 2016). "EGFR mutation was associated with female, adenocarcinoma histology, never-smoking status, and Asian ethnicity." (PMID 27191886, 2016). "Our results regarding the expression of EGFR, HER2 and HER3 are comparable to previously published results, with the possible exception of EGFR expression in I-type adenocarcinomas, where we found 3+ expression in 38% of the cases, compared with 4% expression and 19% 3+ expression in other studies." (PMID 27070783, 2016). "Non-adenocarcinoma patients harboring EGFR mutations had significantly shorter DFS and OS compared to EGFR-mutated adenocarcinoma patients (15.0 versus 39.0 months, log-rank χ2 = 15.075, P < 0.001 for DFS; 30.1 versus 62.6 months, log-rank χ2 = 32.665, P < 0.001 for OS)." (PMID 27072585, 2016). "The frequency of EGFR testing was 16.8% overall and 22.6% for stage IV adenocarcinoma patients." (PMID 27294665, 2016).
adenocarcinoma (continued). "EGFR gene mutations/overexpression in NSCLC patients are associated with adenocarcinomas, female, Asian race, or non-smoker." (PMID 27203390, 2016). "Elderly females who never smoked and possessed 1–20 mm stage I adenocarcinomas in the right side exhibited a higher frequency of EGFR mutations." (PMID 26739511, 2016). "VAMP2-NRG1 was reported in a 67-year-old never-smoker woman with adenocarcinoma with no mutation in EGFR, KRAS and BRAF and with no fusion genes involving ALK, ROS1 or RET." (PMID 27626312, 2016). "However, in this population, the efficacy of EGFR TKIs seemed to be inferior than that in patients with adenocarcinoma histology." (PMID 27811976, 2016). "NSCLC patients with adenocarcinoma were also far more likely to carry the EGFR mutation (adenocarcinoma vs. non-adenocarcinoma: 38.0% vs. 11.7%; OR: 4.1, 95% CI: 3.6 to 4.8) in overall participants." (PMID 27738317, 2016). "Studies have shown that patients with no smoking history, female sex, adenocarcinoma histologic type, Asian ethnicity, or EGFR mutations are predictive of EGFR TKI treatment." (PMID 26979333, 2016). "EGFR mutations are most common in Asian populations, nonsmokers, females and those with adenocarcinoma histology." (PMID 27072585, 2016). "Patients who are Asian, female, non-smokers, and have adenocarcinoma are more likely to harbor an EGFR mutation, which is consistent with previous studies." (PMID 27738317, 2016). "However, CEA was an independent predictive and prognostic factor only for EGFR wild-type adenocarcinoma patients and EGFR L858R adenocarcinoma patients." (PMID 27072585, 2016). "A recent study reported similar efficacies of epidermal growth factor receptor tyrosine kinase inhibitors (EGFR‐TKIs) in patients with EGFR mutation‐positive adenocarcinoma in terms of ORR, PFS, and OS, irrespective of the timing of treatment." (PMID 26880708, 2016). "Median levels and positive rates for CEA, Cyfra21-1 or SCCA were similar regardless of EGFR mutation status in adenocarcinoma patients." (PMID 27072585, 2016). "This type of lesion is known as TRU-type adenocarcinoma and is prevalent among females and non-smokers, and is associated with EGFR mutation." (PMID 27575252, 2016). "In addition, KRAS mutations, as well as other driver mutations including EGFR variants, have been shown to be either clonal or sub-clonal in NSCLC adenocarcinoma." (PMID 27448974, 2016). "The epidemiological study of EGFR mutations demonstrated higher frequency among adenocarcinoma histology, never-smoking status, and Asian ethnicity." (PMID 27191886, 2016). "These drugs have demonstrated higher responses in specific non-tobacco-using groups: Asian females with adenocarcinoma-type histology and EGFR mutations." (PMID 26739511, 2016). "It was found that EGFR mutations are associated with EGFR-TKIs sensitivity as well as East Asian ethnicity, female gender, no history of smoking and adenocarcinoma histology." (PMID 27217997, 2016). "EGFR mutations in NSCLC are more common in adenocarcinomas, females, never-smokers and ethnic Asians." (PMID 27483001, 2016). "Finally, an entire lung lobe from a tri-transgenic animal revealed adjacent regions of adenocarcinoma with different patterns of human EGFR staining, suggesting that distinct cell populations expressed either Kras or EGFR." (PMID 26047463, 2015). "In recent years, the clinical benefits of TKIs were discovered in EGFR mutation, nonsmokers, women, adenocarcinoma, and Asian ethnicity patients." (PMID 26609535, 2015). "Activating EGFR mutations predominate in never-smokers, females and tumors with adenocarcinoma histology." (PMID 25663915, 2015). "Small-molecule EGFR-TKI drugs have shown survival benefits in certain patient subpopulations, including female gender, Asian ethnicity, non-smokers, adenocarcinoma, and specific mutations of the EGFR kinase domain." (PMID 25888731, 2015).
adenocarcinoma (continued). "This study showed that miR-183 expression was significantly higher in adenocarcinoma with EGFR exon 19 mutation than in those without this mutation." (PMID 26170125, 2015). "While EGFR mutations are more commonly observed in patients with these clinical characteristics (i.e., Asian ethnicity, adenocarcinoma histology, etc.), they can occur in patients who do not fit these characteristics as well." (PMID 26310719, 2015). "These human adenocarcinomas of the middle ear and ELSTs displayed EGFR activation." (PMID 26027747, 2015). "Previous studies have reported that common EGFR mutations in the tyrosine kinase domain are more frequent in patients with adenocarcinoma histology, a never smoking history, and an East Asian ethnicity." (PMID 26090892, 2015). "Studies in different populations identified some subgroups (adenocarcinoma histology, women, never-smokers and East Asian ethnic origin) with higher EGFR active mutation rate." (PMID 26599344, 2015). "As for EGFR mutations, several reports have identified the EML4-ALK fusion protein predominantly in young female never-smokers with adenocarcinoma, although the presence of this fusion protein is mutually exclusive with EGFR mutation." (PMID 25760072, 2015). "Adenocarcinoma is the most common subtype of NSCLC and is frequently associated with the genetic alteration of epidermal growth factor receptor (EGFR), such as deletion in exon 19, L858R mutation or wild-type EGFR amplification." (PMID 26268703, 2015). "We also assessed the association between the RT response and histologic subtype (adenocarcinoma versus non-adenocarcinoma) and EGFR status (wild type versus mutation) of adenocarcinoma in these patients." (PMID 26720170, 2015). "We conducted an exploratory analysis to assess whether the benefit of TKIs in patients with wild type EGFR was related to histological type (adenocarcinoma/squamous cell carcinoma)." (PMID 25547901, 2015). "In this patient, both EGFR mutant adenocarcinoma and SCLC had been observed at different times." (PMID 25758528, 2015). "EGFR mutations are more common in never-smokers, in patients with Asian ethnicity, and in patients with adenocarcinoma histology." (PMID 26366316, 2015). "It is possible that selection for CD49+/EpCAM+ cells in combination with culture conditions to increase ErbB3 expression over EGFR expression may increase the likelihood of generating luminal adenocarcinomas." (PMID 26228788, 2015). "The effect of the EGFR mutation on RFS in never-smokers with adenocarcinoma warrants further study in a large prospective cohort." (PMID 25806093, 2015). "PCG did not improve ORR, PFS, and OS compared to PC chemotherapy alone for NSCLC in a clinically selected population excluding non-smoking adenocarcinoma or mutated EGFR." (PMID 26493267, 2015). "Adenocarcinoma compositions could alter the EGFR mutation status of SQCLC, so whether the relevant mutation in SQCLC samples is caused by the inclusion of adenocarcinoma compositions is controversial." (PMID 25886585, 2015). "Additionally, we detected one infrequent EGFR mutation in a sarcomatoid PDX and one BRAF mutation in an adenocarcinoma model." (PMID 25470237, 2015). "Despite this activation, sequencing of exons 19-21 of EGFR in the 2 human adenocarcinomas of the middle ear did not reveal activating or resistance mutations (data not shown), suggesting other mechanism for EGFR activation." (PMID 26027747, 2015). "Also, the protein was silenced frequently in males, smokers, non-adenocarcinomas and in EGFR wild-type patients." (PMID 25120651, 2014).
adenocarcinoma (continued). "The patients most likely to harbor ALK rearrangement were young, never or light smokers with poorly differentiated adenocarcinoma, especially with signet ring cell features, comparing with EGFR mutation or wild type cohort." (PMID 24404167, 2014). "Considering the evidence that Asian, female, non-smoking, and adenocarcinoma patients were more likely to be EGFR mutated, and rates of EGFR mutation in brain metastases of NSCLC were 44%-63% in East Asian population." (PMID 24884773, 2014). "EGFR mutations were found more frequently in women (110/185, 59.5%), adenocarcinoma (183/185, 98.9%), and non-smokers (106/185, 57.3%) (P < 0.001)." (PMID 25152277, 2014). "The PFS in this study was very similar with that in patients treated with gefitinib in IPASS study, which enrolled patients with clinical enrichment of EGFR mutation, including East Asian, female, non-smoker or light smoker and adenocarcinoma." (PMID 24836053, 2014). "Since their identification, it was clear that EGFR mutations, more frequently observed in never smokers, adenocarcinoma histology, women and Asiatic patients, outline a distinct subgroup of NSCLC." (PMID 25505694, 2014). "With respect to adenocarcinoma, mutations in the ras oncogene pathway (smokers) or the epidermal growth factor receptor pathway (non-smokers) can lead to tissue growth dysregulation, and ultimately adenocarcinoma." (PMID 24708840, 2014). "As a secondary assessment, we compared adenocarcinoma patients with and without epidermal growth factor receptor (EGFR) mutation." (PMID 25490772, 2014). "He identified 1 of 12 patients who had the EML4-ALK fusion gene and an EGFR mutation; the patient was a Chinese female non-smoker with a histologic adenocarcinoma." (PMID 25360721, 2014). "Certain patient and tumor characteristics such as adenocarcinoma histology, never-smoking status, female sex and East Asian origin, increase the probability of having EGFR mutations." (PMID 25594059, 2014). "EGFR mutations are known to be associated with clinical characteristics such as never-smoking status, female gender, adenocarcinoma histology and South-East Asian ethnicity." (PMID 25264519, 2014). "While EGFR (epidermal growth factor receptor) is commonly mutated in adenocarcinoma of never smoker patients, the mutations in other genes are much less common than in the smoker patients." (PMID 24894543, 2014). "Somatic mutations in the EGFR gene play key roles in determining the sensitivity of NSCLC patients treated with EGFR inhibitor drugs; however, most of the patients who respond to EGFR kinase inhibitors are the adenocarcinoma subtype of NSCLC." (PMID 24885564, 2014). "Moreover, elevated EphA2/ephrin-A1 expression was associated with female gender, reduced smoking status, adenocarcinoma type, well differentiated and p-stage IA NSCLC and EGFR gene mutations." (PMID 24495444, 2014). "HER-2 mutations are present in about 2-4% of NSCLC, especially in women, never-smokers, Asian patients and in adenocarcinomas without EGFR or K-RAS mutations." (PMID 24898067, 2014). "It is known that a mutation in the EGFR gene, clinical characteristics like female sex, non-smoking status and Asian ethnicity, adenocarcinoma histology and skin toxicity reported during the treatment, give an increased response to EGFR inhibitors." (PMID 24661457, 2014). "For example, K-ras mutations are more frequently found in adenocarcinomas arising in smokers while epidermal growth factor receptor mutations are more frequently found in adenocarcinomas arising in never smokers." (PMID 24722238, 2014). "The overall survival of patients with EGFR activating mutations among all 629 adenocarcinomas was significantly longer regardless of metastatic status, log rank p < 0.001." (PMID 24991207, 2014).
adenocarcinoma (continued). "A number of molecular aberrations have been identified in non small cell lung cancer (NSCLC), including EGFR, BRAF, HER2 mutations, EML4-ALK, ROS1 and RET rearrangements in adenocarcinoma; FGFR mutations/amplifications, DDR2 or PIK3CA mutations in squamous cell carcinoma." (PMID 24898067, 2014). "Our results are consistent with those of recent studies reporting that the rate of EGFR mutations is higher among Asians (including Japanese), females, nonsmokers, and adenocarcinomas." (PMID 25152277, 2014). "The incidence of EGFR mutations in the Caucasian population is approximately 10% and higher still in never-smokers, in the adenocarcinoma subtype, and in women." (PMID 24661457, 2014). "Cytology of the pleural fluid revealed adenocarcinoma with an EGFR mutation of an exon 19 deletion without a T790M mutation." (PMID 24555578, 2014). "Female, never smoker, ECOG PS≤1, adenocarcinoma, EGFR activated mutation and high level of miR-200c expression were the main predictors for longer OS in univariate analysis." (PMID 25277203, 2014). "EGFR mutations were detected in 53.2% of NSCLCs and were significantly associated with adenocarcinoma, female sex, and no smoking history." (PMID 25152277, 2014). "Encouraging new treatments [including epidermal growth factor receptor-tyrosine kinase inhibitors (EGFR-TKIs), anaplastic lymphoma kinase inhibitors, pemetrexed and bevacizumab for adenocarcinomas] have benefited specific patients with advanced or recurrent NSCLC." (PMID 24944713, 2014). "Of 32 patients with adenocarcinoma, 14 were found to be positive for the EGFR mutation, 14 were negative for the EGFR mutation and 4 patients were positive for anaplastic lymphoma kinase (ALK) fusion." (PMID 25490772, 2014). "The rates of EGFR mutations were 26.19% in NSCLC and 40.76% in adenocarcinoma (ADC)." (PMID 25162713, 2014). "This was subsequently identified by studies, which consistently demonstrated that mutations in the tyrosine kinase domain of EGFR are more commonly found among females, never-smokers, Asian individuals and those exhibiting adenocarcinomas." (PMID 25364399, 2014). "The drug exhibits efficacious anticancer activity, particularly in patients with clinical features including EGFR gene mutations, a history of never smoking, adenocarcinoma histology, female gender and Asian origin." (PMID 23761825, 2013). "EGFR-mutated adenocarcinomas had a higher prevalence of females in the never smokers compared with the heavy smokers (P<0.001)." (PMID 24179496, 2013). "Meanwhile, we found that TKIs sensitive EGFR mutations were associated with the female gender (p < 0.001), non-smoking history (p = 0.045), and adenocarcinoma subtype (p < 0.001)." (PMID 24351833, 2013). "The median OS was significantly better in patients with adenocarcinoma (P = 0.014) and patients who had never smoked (P = 0.040), whereas it was unrelated to other factors such as age, EGFR mutation, and ERCC1." (PMID 23940741, 2013). "Epidermal growth factor receptor (EGFR) mutation status was not available for most (75%) patients with adenocarcinoma as our cohort included patients from as early as 2000." (PMID 23530866, 2013). "Second biopsy after cytotoxic chemotherapy for SCLC with an EGFR mutation revealed transformation to adenocarcinoma in various reports, indicating that the SCLC component is more sensitive to cytotoxic chemotherapy than the adenocarcinoma component." (PMID 24195468, 2013). "EGFR mutations are more commonly identified in the adenocarcinomas of never smokers, while KRAS mutations are more frequent in heavy smokers." (PMID 24179496, 2013). "EGFR mutation positive patients were more likely to be female, never-smokers, never-drinkers and to have adenocarcinoma." (PMID 23468851, 2013). "TKIs sensitive EGFR mutations were more frequently found in female patients (p < 0.001), non-smokers (p = 0.047) and adenocarcinomas (p < 0.001)." (PMID 24351833, 2013).